OTUB2 (OTU deubiquitinase, ubiquitin aldehyde binding 2)
Diseases named in the same sentence as OTUB2 in open-access papers (continued):
Sharing a sentence is not in itself a finding about the gene and the disease.
cancer (20 papers, 2015 to 2026). A tumor composed of atypical neoplastic, often pleomorphic cells that invade other tissues. "For instance, OTU deubiquitinase, ubiquitin aldehyde binding 2 (OTUB2) expression was significantly enhanced in EC, which was associated with poor prognosis of cancer patients." (PMID 37478120, 2023). "OTUB2 is likely to cause cancer and other malignant diseases while maintaining normal human development and physiological function." (PMID 35309903, 2022). "OTUB2 (otubain-2) has been shown to be associated with various human diseases, including cancer, in which its deubiquitination of transcriptional regulators YAP and TAZ promotes metastasis." (PMID 34203106, 2021). "OTUB2 may be a potential drug target to suppress cancer progression for patients harboring RAS mutations." (PMID 35414786, 2022). "OTUB2, a cysteine protease with deubiquitinating enzyme activity, has garnered increasing attention for its effects on malignant tumor progression." (PMID 40296903, 2025). "How OTUB2 functions differently from other DUBs in regulating PD-L1 abundance in other cancers needs to be further studied in the future." (PMID 38167274, 2024). "The IHC results revealed that OTUB2 was more highly expressed in cancer tissues than in adjacent paracancerous tissues." (PMID 38167274, 2024). "We first quantitatively assessed OTUB2 protein expression in human LUSC specimens by immunohistochemistry (IHC) and compared the differential expression of OTUB2 between cancer tissues and adjacent paracancerous tissues." (PMID 38167274, 2024). "This motivates the development of OTUB2 as a biomarker for cancer diagnosis and a prognostic factor for multiple human cancers." (PMID 38167274, 2024). "In this study, we demonstrate OTUB2-mediated PD-L1 regulation as a common feature in various human and mouse cancers, particularly in NSCLC." (PMID 38167274, 2024). "Since OTUB2 can promote cancer progression by regulating Hippo, NF-kB and Akt/mTOR pathways, we next investigated the effects of OTUB2-IN-1 on regulating Hippo, NF-κB and Akt/mTOR pathways." (PMID 38167274, 2024). "In paired patients, OTUB2 was also upregulated in the majority of cancer tissues compared to adjacent paracancerous tissues." (PMID 38167274, 2024). "In this study, we presented preclinical evidence, providing proof-of-concept data indicating that targeting OTUB2 with a specific inhibitor, OTUB2-IN-1, is an effective therapeutic strategy for the treatment of cancers." (PMID 38167274, 2024). "Although OTUB2 is theoretically overexpressed in diseases such as cancers, its basic expression in normal cells should also be considered." (PMID 35309903, 2022). "OTUB2 determines cell differentiation in osteoblasts, inhibits β-cell death in pancreatic islet tissue, and accelerates cancer progression in some cancer tissues." (PMID 35309903, 2022). "OTUB2 promoted cancer stemness and metastasis by deubiquitinating and stabilizing Yap/Taz in a manner independent of Lats1/2." (PMID 33869224, 2021). "Additionally, OTUB1 and OTUB2 served as pivotal components in maintaining cancer stemness and promoting metastasis via deubiquitination and stabilization of YAP proteins in gastric and colon cancer, respectively." (PMID 40469292, 2025). "Notably, a specific inhibitor developed in a recent study, OTUB2-IN-1, was found to inhibit the catalytic activity of OTUB2 and exert strong inhibitory effects on multiple types of cancer." (PMID 39776804, 2025). "In this study, we found that OTUB2 inhibition may also inhibit cancer progression by suppressing Hippo signaling, AKT/mTOR signaling and NF-κB signaling in addition to the reduction of PD-L1 expression." (PMID 38167274, 2024). "Consistently, analysis of the LUSC cohort profiled by the TCGA also revealed that OTUB2 was more highly expressed in cancer tissues than in normal tissues, while the CTL signature genes CD8A and GZMB were expressed at significantly lower levels in cancer tissues than in normal tissues." (PMID 38167274, 2024).
cancer (continued). "Taken together, our data suggest that OTUB2 may be a potential therapeutic target for cancer immunotherapy." (PMID 38167274, 2024). "Similarly, we observed that across multiple cancer types, OTUB2 expression was negatively correlated with the expression of the CTL signature genes GZMB, GZMA and CD69." (PMID 38167274, 2024). "The dual role of OTUB2 in cancer may be the result of its interaction with different proteins as a deubiquitinating enzyme." (PMID 38819228, 2024). "OTUB2 stimulates the growth of cancer by acting on oncogenic proteins." (PMID 38819228, 2024). "The biological function of OTUB2 related to cancer development seems to be complex." (PMID 38167274, 2024). "In addition to TERT, BLCAP, and KBTBD8, we also observed low levels of damage induction in UV-irradiated melanocytes at a number of other recurrent mutations in the promoters of known or suspected cancer genes (i.e., TCF3, TOP2A, NUMB, FOSB, and OTUB2)." (PMID 37169747, 2023). "Besides OTUB1, other DUBs, such as USPs family (USP1, USP7, USP8, USP15, USP22), OTUs family (OTUD7B, OTUD6B, A20, and OTUB2) and other DUBs have been identified to regulate the progression of various cancers and applied for clinical cancer therapy." (PMID 35715413, 2022). "This review makes a general description and appropriate analysis of OTUB2’s regulation in different cell signaling pathways, and connects OTUB2 with cancer from the research hotspot perspective of DNA damage repair and immunity, laying the theoretical foundation for future research." (PMID 35309903, 2022). "Instead, we speculate that the metastasis of multiple cancers induced by KRT80 is also attributable to OTUB2’s firmly support." (PMID 35110531, 2022). "The basal level of OTUB2 expression in normal tissue is self-evidently important for development and physiological functions, but relatively speaking, targeting excessive OTUB2 in diseases such as cancers may be a promising therapeutic target." (PMID 35309903, 2022). "An in vivo DUB cDNA screen identified OTUB2 as an enhancer of cancer metastasis." (PMID 33869224, 2021). "Finally, the Otubain-2 (OTUB2) deubiquitinating cysteine protease was recently identified as a cancer stemness and metastasis-promoting factor that deubiquitinates and activates YAP/TAZ." (PMID 31619007, 2019). "Moreover, the expression of OTUB2 mRNA and protein could be regulated by FOXD3-AS1 derived from cancer-associated fibroblasts (CAFs)." (PMID 42003916, 2026). "Notably, OTUB2 were significantly upregulated in the cancer tissues of these two cancer types compared with adjacent paracancerous tissues, suggesting that OTUB2 may play an immunoregulatory role in the TME." (PMID 38167274, 2024). "Therefore, OTUB2, as an intermediate molecule, both undertakes the downstream effects of RAS mutations and triggers YAP/TAZ-mediated oncogene expression based on its deubiquitination function (K48), forming a chain reaction and worsening cancer progression." (PMID 35309903, 2022). "Consistently, the mRNA and protein expressions of OTUB2, EIF4A3, and TPI1 were increased in TNBC tissues and cell lines, as compared to para-carcinoma tissues and MCF10A cells." (PMID 41857621, 2026). "Interestingly, our results showed no inhibitory effect of OTUB2 deficiency on cell growth; however, whether OTUB2 deficiency affects cancer metastasis was not investigated in this study and deserves further investigation." (PMID 38167274, 2024). "We also demonstrated the connection between OTUB2 and CD8 such that the expression of OTUB2 was inversely correlated with the expression of CD8 in various cancers, especially in LUSC." (PMID 38167274, 2024). "Interestingly, OTUB2-IN-1 treatment only significantly reduced the expression of phosphorylated Akt in B16-F10 tumors and significantly reduced the expression of phosphorylated p65 in KLN205 tumors, suggesting that OTUB2 may possess more general roles in regulation of PD-L1 in various cancer types." (PMID 38167274, 2024).
cancer (continued). "Moreover, we demonstrate that OTUB2 is a general regulator of PD-L1 since genetic depletion or pharmaceutical inhibition of OTUB2 expression profoundly impacts PD-L1 protein stability in multiple cancers, especially in tumors generally expressing low levels of PD-L1." (PMID 38167274, 2024). "EGFR, followed by RAS activation, induces SUMOylation of Otubain-2 (OTUB2), thereby promoting deubiquitination of YAP/TAZ and stabilizing them in cancer cells." (PMID 36294681, 2022). "OTUB2 can stably activate the NF-kappaB pathway through K48 type deubiquitination of TRAF6 and maintenance of phosphorylated p65, resulting in pathological manifestations of cancer." (PMID 35309903, 2022). "Hence, OTUB2 sumoylation represents a novel mechanism that links the oncogenic EGFR-RAS pathway to Yap/Taz activation and a potential therapeutic target for cancer treatment." (PMID 33869224, 2021). "We demonstrated that OTUB2-IN-1 reduced PD-L1 protein turnover through inhibition of OTUB2 catalytic activity rather than blocking the OTUB2-PD-L1 interactions and exhibited strong growth-suppressive effects on multiple cancers by attenuating immunosuppression." (PMID 38167274, 2024).
infection (3 papers, 2020 to 2025). The state of being infected such as from the introduction of a foreign agent such as serum, vaccine, antigenic substance or organism. "Among these, one group containing OTUB1, OTUB2, OTUD4, OTUD5, OTUD6B, and OTUD7B showed obvious upregulation 6 h post-infection, followed by downregulation 12 h post-infection." (PMID 37650650, 2023).
inflammation (1 paper, 2024). Aberrant reaction of the microcirculation characterized by movement of fluid and leukocytes from the blood into extravascular tissues. "This study identifies OTUB2 as a key factor regulating intestinal homeostasis and inflammation, providing new therapeutic opportunities for the treatment of intestinal inflammation." (PMID 39358938, 2024).
OTUB2 also shares sentences with these, for which no sentence is quoted: hepatocellular carcinoma (3 papers); airway hyperresponsiveness (1); Anxiety (1); asthma (1); cholangiocarcinoma (1); chronic kidney disease (1); depression (1); glioblastoma (1); head and neck squamous cell carcinoma (1); intrahepatic cholangiocarcinoma (1); ischemia (1); ischemic stroke (1); lung adenocarcinoma (1); lung squamous cell carcinoma (1); lymph node metastasis (1); prostate carcinoma (1).